HIF1A (hypoxia inducible factor 1 subunit alpha)
Diseases named in the same sentence as HIF1A in open-access papers (continued):
Sharing a sentence is not in itself a finding about the gene and the disease.
tumor (continued). "Through regulation of AKT activation and HIF1α, MAP17 facilitates the Warburg effect to promote tumor growth in HCC." (PMID 33832535, 2021). "Furthermore, ROS can act both at the level of early tumor development and metastases, thus working as secondary messengers in the activation and maintenance of signaling pathways involved in cell proliferation, particularly through NF-kB or HIF-1α, survival, angiogenesis, and EMT." (PMID 34205678, 2021). "With increasing levels of tumor PD-L1, the expression of transcription factors for Th1, Th2, or M1 macrophages, including NFKB1, GATA3, HIF1A, STAT4, TBX21, IRF8, and STAT1, was downregulated." (PMID 33754038, 2021). "Under a hypoxia microenvironment, the elevated HIF-1α induced the expression of P4HA1, which remodeled ECM and promoted tumor invasion, EMT, angiogenesis, and so on." (PMID 33816483, 2021). "Tumor cells depend on MCT4 and, to a lesser extent, on MCT1 for lactate export, and MCT4 is expressed in a HIF-1α dependent manner." (PMID 33466735, 2021). "Hypoxic tumor cells survive these harsh conditions by activating the transcription factor HIF, which is composed of an oxygen-sensitive HIF-1α subunit and a constitutively produced HIF-1β subunit." (PMID 34298883, 2021). "Both NF-κB and Nrf2 have been proposed as promising targets for infection, while HIF-1α and PI3K have been defined as the key proteins of the tumor microenvironment, targeting cancer immunotherapy and relapse problems." (PMID 34577146, 2021). "Here, we discovered that HIF-1α and HECTD2 were enhanced in RCC, and in-vivo studies testified that overexpressing HECTD2 and HIF-1α hampered apoptosis and induced tumor growth of RCC cells." (PMID 35004677, 2021). "VEGF-A activates tumor angiogenesis by binding to VEGFR, and HIF-1α enhances this process by upregulating VEGF expression." (PMID 33746989, 2021). "HIF-1α contributes to the recruitment of bone marrow-derived CD45+ myeloid cells including macrophages and further regulates tumor angiogenesis and invasion indirectly." (PMID 34202979, 2021). "At the same time, 16a catalyzed H2O2 to O2 in the tumor microenvironment (TME) and thereby overcame hypoxia by achieving in situ O2 supply and reduce HIF-1α hypoxic staining signal." (PMID 34452256, 2021). "Furthermore, it has been reported that tumor-derived exosomes may carry different factors involved in the activation of EMT program including TGFβ, caveolin-1, HIF1α, vimentin and β-catenin thus improving the migration ability of cells inside a tumor and contributing to stromal remodelling." (PMID 36046089, 2021). "HIF-1α and HIF-2α, as most studied members of HIFs, are broadly expressed in varieties of tumor types." (PMID 34389031, 2021). "Higher HIF-1α gene expression in both chemo-resistant NSCLC and mesenchymal polarised tumours was observed." (PMID 34298636, 2021). "Many studies have displayed the close relationship between hypoxia and tumor dormancy, and here we have demonstrated that DEC2 was positively correlated with HIF1α expression in SACC cells." (PMID 33990215, 2021). "HIF-1α and HIF-2α have shown positive correlation with clinical-pathological parameters in OSCC, tumor size and MVD, and their knock down inhibited tumor angiogenesis and tumor growth in a nude mice xenograft model." (PMID 33445558, 2021). "The expression of HIF-1α and PD-L1 down-regulated, resulting in enhanced CMT and immune response and inhibited the PD-1/PD-L1 axis, which significantly prolonged tumor recurrence time and inhibited tumor metastasis." (PMID 34277702, 2021). "In vivo studies verified that treatment with ginsenoside CK not only inhibited tumor growth (reduced tumor volume and weight) but also suppressed the local EMT process resulting from the regulation of HIF-1α/NF-κB signaling." (PMID 34073155, 2021). "In the present study, the expression of HIF-1α and VEGF in the tumor decreased after both IPN and cisplatin-IPN embolization compared with that in the negative control group." (PMID 33685316, 2021).
tumor (continued). "To further determine the effect of HIF‐1α expression on the activation of fibroblasts, we examined the effects of TGF‐β1, tumour cell CM and Cocl2 on Acta2 and Col1a2, which are markers of CAFs." (PMID 33943003, 2021). "Instead, we will focus on HIF1α and HIF2α as biomarkers and/or targets for RCC tumor potential therapeutics, which is a popular area that has been growing in the past decade or so." (PMID 34384473, 2021). "In the time window of vascular normalization, hypoxia of the tumor microenvironment was improved by ORI, the expression of HIF-1a was downregulated." (PMID 33976735, 2021). "These treatments affected CEP mobilization, tumor vessel number, and tumor expression of VEGF and hypoxia inducible factor-1 (HIF-1α) differently." (PMID 34771577, 2021). "Structural recruitment of the C-terminal transactivation domain (CTAD) of HIF-1α and cysteine/histidine rich domain 1 (CH1) of CBP/p300 leads to transcription of VEGF genes, prominent for pro-angiogenic functions in tumor progression." (PMID 34957091, 2021). "In SGC-7901 cells, melatonin impaired VEGF secretion and reduced SUMO-specific protease 1, HIF-1α, and VEGF in provoking the inhibition of tumor growth." (PMID 34209857, 2021). "HIF-1α is recruited to miR-182-5p promoter to transcriptionally upregulate miR-182-5p, which facilitates NPC progression by targeting the tumor suppressor ZFP36L1." (PMID 34465330, 2021). "Mechanistically, knockdown of CTNND1 promoted tumor cells EMT and homing to the bone via upregulation PI3K/AKT/HIF-1α/CXCR4 pathway." (PMID 34830862, 2021). "Some studies on biochemical changes in tumor cells have shown that high hypoxia-inducible factor 1α (HIF-1α) and vascular endothelial growth factor A (VEGF-A) expression in viable tumors is conducive to tumor angiogenesis." (PMID 34900679, 2021). "Several studies reported higher expression of HIF-1α and HIF-2α in TC than in normal thyroid or benign lesions." (PMID 34684168, 2021). "Consistently, shRNA knockdown of CHCHD4 was shown to significantly block HIF-1α stabilisation and HIF target gene expression in tumour cells in response to hypoxia, and block tumour growth and angiogenesis in vivo." (PMID 33599699, 2021). "In some cancers, isoforms with only LDHA subunits have the highest efficiency at converting pyruvate to lactate and are correlated with increased HIF-1α and VEGF expression, increased tumor size, enhanced metastatic potential, and thus a poor prognosis." (PMID 33718271, 2021). "Immunoexpression of both HIF-1α and LOXL-2 was analyzed both quantitatively and qualitatively and compared with tumor stage, nodal stage, clinical stage, and histological grade." (PMID 33639646, 2021). "Tumor specimens underwent immunohistochemical staining for PD‐L1, PD‐L2, GLUT1, HIF‐1α, VEGFR2, VEGF‐C, and β2 adrenergic receptor." (PMID 34363337, 2021). "Knockout of HIF1A, PDGFD or PDGFRA in U251 cells inhibits cell growth and invasion in vitro and eradicates tumor growth in vivo." (PMID 34470658, 2021). "They showed expression levels of HIF-1α and Cav-1 to be upregulated in IDH-wild type tumours, and Cav-1 levels to be significantly correlated with high HIF-1α expression." (PMID 34490102, 2021). "Although the mechanism of action of cardiac glycosides is unclear, digoxin treatment suppresses neovascularization by decreasing HIF-1α levels in P493 and PC3 tumor xenografts in vivo." (PMID 34200019, 2021). "Tumor-derived lactate, a byproduct of tumor glycolysis, leads to M2-like TAM polarization by activating HIF-1α and subsequent inducing ARG1 and VEGFA." (PMID 34389031, 2021). "Upon RDC11 administration in human colorectal adenocarcinoma (HCT116 cell line) in vivo, levels of HIF-1α were significantly reduced and, consequently, VEGF levels and angiogenesis, leading to a reduction in tumor size." (PMID 33673417, 2021). "Such an aberrant HIF-1α activation in TAMs promoted the TAM-pro-tumoral function and tumor development." (PMID 34831183, 2021).
tumor (continued). "In summary, this study indicates that HIF‐1α is highly expressed in CAFs, and HIF‐1α‐expressed fibroblasts secreted CCL5 by activating NF‐κB signalling pathway, thus promoting the tumour growth of LC." (PMID 33943003, 2021). "Further, we demonstrated that silencing ATF5 phenocopies HIF1α knockdown in tumorigenic properties in vitro and inhibited ESCA tumor angiogenesis and proliferation in vivo." (PMID 33980247, 2021). "We report that β-escin enhances autophagy, while inhibiting HIF-1α stability and extracellular matrix (ECM) production in the OvCa tumor microenvironment (TME)." (PMID 34439084, 2021). "The HIF-1α expression and the LOXL-2 expression were compared with the tumor category, nodal stage, clinical TNM stage, and histological grade using Kruskal–Wallis test." (PMID 33639646, 2021). "Further, both HIF-1α and HIF-2α upregulate angiogenic molecules VEGF, IL-6, and the tyrosine-protein kinase receptor (Tie2) receptor in TAMs, thus promoting tumor angiogenesis." (PMID 34988021, 2021). "We generated specific Nbs against HIF-1α PAS B domain as novel tools to interrupt the interaction of the two subunits and to inhibit the transcriptional activation of tumor related targeted genes of HIF-1." (PMID 34830219, 2021). "In accordance with that, knockdown of PLOD3 inhibited HIF-1α accumulation via the ERK signaling pathway under hypoxia, suggesting that PLOD3 had the potential to regulate the tumor microenvironment." (PMID 34239923, 2021). "Hypoxia, specifically hypoxia-inducible factor 1 alpha (HIF-1α), appears to be one of the most critical stresses and was shown to be essential in M2-type TAM generation from Ly6Chi monocytes inside a tumor." (PMID 34025641, 2021). "Proteins related to cell proliferation, growth, and apoptosis like BCL-X, HIF-1α, HNF-3β, and HO-1/HMOX1 were also downregulated, that is, related to tumor progression, whereas upregulation of E-cadherin (CDH1) was observed after chrysin treatment." (PMID 35096000, 2021). "In a hypoxic tumor microenvironment, M2-like TAMs can produce high levels of VEGF-A and hypoxia-inducible factor (HIF)-1α." (PMID 33746989, 2021). "RECK is a tumor suppressor and hypoxia significantly downregulates RECK mRNA and protein expression, while the effect is abolished by knockdown HIF‐1α with respective siRNAs." (PMID 33463054, 2021). "In conclusion, this study showed the importance of HIF-1α and HIF-2α in tumor growth arrest and proliferation." (PMID 34824343, 2021). "In this study, we found that ID1 protein is upregulated in response to HIF1α inhibition, and ID1 in turns supports HIF1-independent tumor growth in hypoxia and in vivo." (PMID 34820369, 2021). "In light of the common view that tumor microenvironment is often hypoxic and HIF-1α is a hypoxia-inducible factor, we focused on the effect of HIF-1α on transcriptional regulation of JFK." (PMID 34336836, 2021). "HIF-1α protein (and its isoforms, HIF-2α and HIF-3α) represents the master regulator of the response to hypoxia in both normal and tumor tissues." (PMID 34696251, 2021). "The high expression levels of Nrf2, HIF1α, and VEGF in As3+-exposed-induced tumor samples were further confirmed by immunohistochemistry." (PMID 34758851, 2021). "The protein expression levels of HIF-1α and VEGF-A were confirmed to be significantly downregulated in the tumor lysate." (PMID 33806179, 2021). "We found HKII and HIF-1α increased in PCA, further support metabolic reprogramming to the Warburg effect in tumor cells." (PMID 34220956, 2021).
tumor (continued). "Our results show that following combination treatment with Avastin plus FO and Se, exerts dose-dependent inhibitory effects on the activation of HIF-1α/HIF-2α, HSP90 along with decreased expression of COX-2 in TNBC tumor tissues in a dose-dependent manner." (PMID 33805447, 2021). "Subsequent inhibition of CRIPTO in these xenograft tumors reduces proliferative capacity specifically in cells with high levels of HIF1α, supporting the notion that CRIPTO signaling is necessary for tumor growth in hypoxic domains." (PMID 34576327, 2021). "Many factors influence primary tumor growth and overall metastatic potential including VEGF, HIF1α, and FGF as well as many cytokines and chemokines." (PMID 34371939, 2021). "Recently, nuciferine has been applied in drug-resistant tumor cells, and it was able to regulate MDR proteins as well as reduce the activation of Nrf2 and HIF-1α." (PMID 34680470, 2021). "Collectively, these findings support a notion that HIF-1α-JFK axis is an important regulator that acts to elevate cellular tolerance to hypoxia and contribute to cell survival in promoting breast carcinogenesis." (PMID 34336836, 2021). "The enhanced inhibition of HIF1α by combined targeting of CDK1 or CDK4/6 and HSP90 was observed in multiple tumor cell lines." (PMID 34686682, 2021). "Consistently, the protein levels of TRIM44, p-STAT3, BCL2, MMP9, HIF-1α and PIM1 were all decreased in SPATS2 knockdown tumor tissues, which underpinned the contribution of SPATS2-TRIM44-p-STAT3 axis to tumorigenic events in HCC." (PMID 33391405, 2021). "Next, we measured the expression level of HIF1A, and found that the expression of HIF1A was significantly reduced in si-SNHG6 tumor tissues." (PMID 33663502, 2021). "The results of therapeutic effect in 4T1 tumour-bearing mice showed that when POP-Gel was injected around the tumour, the Ce6 was able to penetrate the tumour and reduce the expression of HIF-1α to low levels after PDT treatment." (PMID 34946732, 2021). "Compared with the other agents, RT+AL-HA-Tyr decreased HIF-1α, Ki67, and VEGF-A expression, and increased γ-H2AX levels in tumor cells." (PMID 33777779, 2021). "HIF-1α and AHR modulate the metabolism of neoplastic and immune cells to impact tumor immunity and progression." (PMID 34712225, 2021). "More importantly, Fuhrman grade in patients with higher profiles of HIF-1α and HECTD2 was generally staged III + IV and tumor stage tended to be pT2/T3." (PMID 35004677, 2021). "Kozlova and colleagues have shown that disruption of the CIN85/PHD2 interaction using CRISPR/Cas9 editing not only led to lower levels of HIF-1α and HIF-2α, but also to significantly impaired tumor growth and migration in a breast carcinoma model (MDA-MB-231)." (PMID 33673417, 2021). "RT+AL-HA-Tyr more significantly reduced 18F-FMISO uptake as well as HIF-1α, Ki67, and VEGF-A expression, and increased γ-H2AX expression in tumor cells compared to the other treatments." (PMID 33777779, 2021). "As a classic response gene of hypoxia-induced factor (HIF1α), CAIX plays a critical role in hypoxic environments through the regulation of cellular acidosis supporting tumor cells survival." (PMID 34685701, 2021). "As a novel oncogene, CIRBP has been shown to increase the expression of HIF-1α by binding to the 3′-UTR of its mRNA, which suppresses the expression of prostaglandin I synthase (PTGIS) and regulates tumor progression." (PMID 34490236, 2021). "Generally, both HIF-1α and HIF-2α show a positive correlation with tumor progression, but with some exceptions." (PMID 34944758, 2021). "The IHC results demonstrated that the staining of HIF-1α, VEGF and CD34 proteins in xenograft tumor tissues from nude mice administrated with ASP (HASP, MASP and LASP) was significantly weaker compared with the PBS group." (PMID 34093799, 2021). "In ovarian cancers, NOX4-derived H2O2 regulates HIF-1α expression which in turn governs VEGF levels, essential for tumor-induced angiogenesis." (PMID 34205998, 2021).
tumor (continued). "In HCC, the suppression of CYP1A2 stimulates HIF-1α upregulation and HGF synthesis to activate MET/PI3K/AKT/NF-κB signaling as well as MMPs, facilitating tumor growth, migration, and invasion." (PMID 33500715, 2021). "The tumor volumes and weights in mice bearing tumor derived from Adv-NC + Lsh1-OR7E156P co-infected cells were the lowest; contrariwise, those in mice bearing tumor derived from Adv-HIF1A + Lsh-NC co-infected cells were the highest." (PMID 34422645, 2021). "The contribution of autophagy to tumour progression was evident in grade III gliomas, in which IL-6, HIF1A (marker of hypoxia) and LC3B (marker of autophagy) were found to co-localise in hypoxic regions within the tumours." (PMID 33803414, 2021). "Hypoxic conditions, often present in brain tumors, induce HIF-1α expression, which further stimulates CXCL12 expression in tumor cells." (PMID 34200145, 2021). "Overexpression of HIF-1α upregulates GLUTs, hexokinase isoform 2 (HK2), pyruvate kinase isoform M (PKM), and other key factors, leading to tumor aerobic glycolytic metabolism." (PMID 34513829, 2021). "Overexpression of HIF-1α reduced the levels of Let-7a, Let-7b, and Let-7d as well as its complement downstream target LIN41 and Aurora B to promote tumor metastasis." (PMID 35008539, 2021). "For example, EF24 effectively reversed sorafenib resistance by degrading HIF-1α and inactivating NF-κB via a VHL tumor suppressor." (PMID 34307125, 2021). "While HIF1α- and c-Myc-related pathways promote the expression of LDH-A, overexpression of the tumor suppressor miR-34a counteracts this effect." (PMID 34680164, 2021). "EZN-2968 treatment decreased mRNA and protein levels of HIF-1α under hypoxic conditions in a dose-dependent manner and significantly delayed tumor growth in DU145 xenografted tumor-bearing mice." (PMID 34200019, 2021). "The α -subunit implies degradation and sensitivity to oxygen, the β-subunit means oxygen independence and the -3α serves as a suppressor or negative regulator for HIF-1α and HIF-2α (tumor promoters due to cellular response to low oxygen)." (PMID 34142021, 2021). "circAGFG1 silencing also reduced the protein expression of HIF-1α and glycolysis-related markers (GLUT1, PGK1, and PKM2) in tumor tissues." (PMID 34013042, 2021). "The clinical significance of HIF-1α and Beclin1 in OSCC patients was evaluated by analyzing the expression level of HIF-1α and Beclin1 in 80 OSCC tissues and pare-cancer tissue (tumor margin adjacent normal tissues) by the scoring of IHC." (PMID 34465721, 2021). "Both HIF-1α and PI3K are major components of the tumor microenvironment (TME), which has been proposed as an essential target for cancer immunotherapy and for overcoming multidrug resistance and cancer relapse problems." (PMID 34208576, 2021). "The overproduction of lactate in glycolytic tumors is also involved in the abnormalization of the tumor vasculature via the inhibition of PHD, which stabilizes HIF-1α and increases VEGF levels in tumor endothelial cells (TECs) and other cells of the TME." (PMID 33804985, 2021). "Here, melatonin induced NRF2, HIF1a and the VEGF protein while reducing the microvessel occurrence and CD31, Ki67-positive tumor cell number and inhibited tumor growth." (PMID 33805996, 2021). "In the present study, we demonstrate that the mitochondrial chaperone TRAP1 is a transcriptional target of HIF1α and that TRAP1 is induced in hypoxic conditions both in fish embryos and in tumor models." (PMID 33934112, 2021). "Studies have suggested E2-EPF role in stabilizing HIF-1α via selectively targeting pVHL in the normoxic situation, and the forced expression of E2-EPF speeds up tumor proliferation, metastasis, and invasion." (PMID 34769401, 2021). "PLOD2 is regulated by HIF-1α, TGF-β1, and microRNA-26a/b through the PI3K-AKT or the TGF-β/Smad signaling pathways in tumor cells." (PMID 33495412, 2021).